CD4 (CD4 molecule)
Diseases named in the same sentence as CD4 in open-access papers (continued):
Sharing a sentence is not in itself a finding about the gene and the disease.
tumor (continued). "This combination therapy not only reduced Ki67 expression and increased CC3 expression in tumor tissues but also shifted macrophage polarization toward an M1 phenotype and enhanced CD4+ and CD8+ T cells infiltration, indicating an augmented immune response." (PMID 40037158, 2025). "Normal tissues adjacent to the tumor (p<0.01) showed greater infiltration of CD4+ lymphocytes than samples from the tumor center." (PMID 40469283, 2025). "The TIMER2.0′ Immune Association’ module analysis indicated a significant correlation between the expression of FOXP3, IL-10, and TGF-β1 and the abundance of tumor-infiltrating CD4+ CD25+ Foxp3+ Tregs, as inferred by the EPIC algorithm." (PMID 41438510, 2025). "The expression of arginase-1 in neutrophils and the level of Apo-A1 within UTUC tumors were negatively correlated with tumor-infiltrating CD4+ T cells." (PMID 40358184, 2025). "CIBERSORT analysis indicated significantly elevated infiltration of immunosuppressive regulatory T cells (Tregs) and M0 macrophages, coupled with a marked reduction in anti-tumor effector cells, such as natural killer (NK) cells and CD4+ T cells (p < 0.05)." (PMID 41614774, 2025). "Regulatory T cells (Tregs) are typically characterized as thymus-derived CD4+ CD25+ FOXP3+ T cells, which play a crucial role in suppressing tumor-associated antigen-specific activation within tumor-draining lymph nodes." (PMID 40432130, 2025). "4Mu was safe and well tolerated, and notably, combined with anti-PD-1 therapy, it synergistically inhibited tumor growth and increased both CD4+ and CD8+ T cell infiltration." (PMID 41226466, 2025). "Particularly, we evaluated the dynamics of tumor infiltration by immune cells expressing CD4, CD8, and granzyme B (GrB)." (PMID 40007542, 2025). "Upon activation, DCs migrate to lymph nodes and prime naïve T cells, initiating CTL-mediated tumor or pathogen elimination and CD4+ Th cell-driven antibody production and memory formation." (PMID 40497988, 2025). "Dendritic cell-derived exosomes (DEX) have shown great potential in priming the immune system by presenting tumor antigens, which active both cytotoxic CD8+ and helper CD4+ T cells, driving a strong anti-tumor immune response." (PMID 40693234, 2025). "In line with this, the knockdown or pharmacological inhibition of LSD1 using compound Z-1 stimulated T-cell killing of gastric cancer cells in vitro, and promoted tumor infiltration by CD4+/CD8+ T cells in tumor xenografts in syngeneic mice." (PMID 40940894, 2025). "We performed multi-site global proteomic profiling on 80 HGSOC tumor samples from 23 patients and mapped the spatial distribution of CD4+ and CD8+ TILs in a subset of samples using IHC." (PMID 40523956, 2025). "PLGA nanoparticles that carry both immune checkpoint inhibitors (such as anti-PD-L1) and cytokines enhance tumor regression mediated by CD4+ T cells." (PMID 40860882, 2025). "While these CD4 + T cell-derived TCRs showed limited tumor killing in a direct cytotoxicity assay in vitro, there is accumulating evidence that CD4 + T cells can execute tumor cytolysis by several other indirect mechanisms." (PMID 41410746, 2025). "By increasing the infiltration of CD8+ and CD4+ T lymphocytes, radiotherapy enhances the ability to identify and eradicate tumor cells, strengthening the anti-tumor immune effect and inhibiting immune escape." (PMID 40740877, 2025). "Simultaneously, RCOR2 inhibited CIITA expression through HDAC1/2-mediated deacetylation of histone H4 at lysine 16, leading to MHC-II silencing in tumor cells and subsequent impairment of CD4+CD8+ T cell immunosurveillance, thereby promoting immune evasion." (PMID 40608411, 2025). "Tumors with IDH1 mutations had a trend toward more fibroblasts and were characterized by a closer proximity of tumor cells to CD4+ T cells, and between macrophages and multiple structural tumor microenvironment components as compared to other subtypes." (PMID 39969434, 2025).
tumor (continued). "Our study found that high-risk patients have lower infiltration of anti-tumor immune cells (memory B cells, plasma cells, CD4+ T cells, NK cells, DCs), while exhibiting higher levels of M2-type TAMs that promote tumor growth and immunosuppression." (PMID 40766310, 2025). "For changes in the immune landscape, we monitored the CD4+T cell populations infiltrating the tumor, specifically the Th17 and Treg populations, as AHR is a master regulator of CD4+T cell development." (PMID 40283908, 2025). "In the PanCK tumor area, we found that the percentages of CD4+ T cells, CD8+ T cells, and neutrophils tended to be higher than those of other cell types (22.75%, 19.36%, and 27.24%, respectively)." (PMID 40422184, 2025). "Overall, this study demonstrates that targeting MSLN can improve neoantigen vaccine induced immune efficacy by reducing apCAFs to interrupt the conversion of naive CD4+ T cells to Tregs, and therefore increase the infiltration of tumor‐specific T cells." (PMID 39887656, 2025). "By contrast, ample evidence of proliferation was observed in tumor cells following CD4 T-cell depletion." (PMID 40299790, 2025). "Increased levels of CD8+ and CD4+ T cell infiltration in tumor tissues of HNSCC are related to a better prognosis." (PMID 39907408, 2025). "ANGPTL1 is prominently expressed in effector memory CD4 T cells and myeloid-derived suppressor cells (MDSCs), potentially contributing to immunosuppression and the regulation of the tumour microenvironment." (PMID 40475773, 2025). "Preclinical studies have shown that GITR agonists promote the activation of CD8+ and CD4+ effector T cells while inhibiting the activity of tumor-infiltrating T cells." (PMID 40242773, 2025). "CXCR2P1 plays a vital role in reshaping the tumor immune microenvironment by promoting greater immune cell infiltration and significantly increasing the proportions of M1 macrophages, CD4+ T cells, and follicular helper T cells." (PMID 40176817, 2025). "The numbers of CD4+ and forkhead box protein P3 (Foxp3)+ T cells infiltrating and accumulating in the RENCA tumor were assessed by immunohistochemical staining with anti‐CD4 and Foxp3 antibodies." (PMID 40371846, 2025). "CD4+ T cells exhibit diverse functions: Th1 exerts anti-tumor effects while Th2, Th17 (context-dependent), and Tregs contribute to immunosuppression." (PMID 41200178, 2025). "For NCI-H226 mouse xenograft tumor model, overexpression of TAGAP on CD4+ T cells inhibited tumor volume and weight; while, TAGAP silencing on CD4+ T cells accelerated tumor progression and increased weight in vivo." (PMID 39998561, 2025). "AgNPs show selective cytotoxic effects on tumor cells, diminishing immunosuppressive factors and improving CD4+ T-cell function." (PMID 40860882, 2025). "A hierarchical clustering analysis reflected high CD4 dissimilarities between blood and tumor cells." (PMID 40164596, 2025). "Overlapping long peptides that encompass both class I and class II peptides have been shown to generate strong T cell responses in numerous studies and many groups have reported that anti-tumor immunity is highly dependent on the presence of CD4 T cells." (PMID 40103827, 2025). "We also probed for changes in other cellular compartments in the tumor including CD4 T cells, γδ T cells, DCs, macrophages, NK cells, and Neutrophils." (PMID 41279375, 2025). "Studies have indicated that B cell deficiency augments the infiltration of CD4+ and CD8+ T cells into the TME, thereby enhancing the responsiveness to chemotherapy in mouse tumor models." (PMID 41285707, 2025). "Contrary to that, CD4+ CD39+ CD103− T-cells residing within the tumor stroma exhibited a highly immunosuppressive phenotype." (PMID 40227655, 2025). "In this approach, EcN was engineered to express peptide arrays that contain both CD4+ T cell and CD8+ T cell epitopes derived from neoantigens, which are generated by somatic mutations in tumor cells." (PMID 40076679, 2025).
tumor (continued). "IHC staining of resection LTFs from 8 tumors representing 5 different tumor types showed reduced total cells (P<0.05), reduced CD4+ cells (P < 0.05) and a trend toward reduced CD8+ cells (P = 0.07) after 48 hours of culture." (PMID 40791544, 2025). "Among them, anti-tumor CD4+ cells such as TH1 are called CD4+ conventional T cells (CD4+ conv T cells)." (PMID 40696413, 2025). "Due to various limitations associated with the use of DCs as vaccines, mature DCs have been developed in vitro and employed as cancer vaccines because they can effectively produce tumor-specific antigens for recognition by CD4+ and CD8+ T cells." (PMID 41155765, 2025). "We did observe an increase in the total number of tumor-infiltrating Treg cells in M002-treated mice, but this was secondary to the overall increase of total TILs and CD4+ T cells." (PMID 39885128, 2025). "Supernatants from CD4+ splenocyte cultures and induced Th17 lymphocytes from young 4T1 tumor-bearing mice were analyzed for OPN secretion." (PMID 40894304, 2025). "Under the stimulation of the tumor inflammatory microenvironment (IM), the reprogramming of Treg cells, as members of CD4+ T cells, enhances their suppression of immune responses, ultimately promoting tumor immune escape or tumor progression." (PMID 40655142, 2025). "Molecular studies demonstrated that the short-term high-salt diet induced the anti-tumor activation of CD4+ T cells, leading to reduced tumor progression." (PMID 40563574, 2025). "In the present study, we developed a novel cancer immunotherapy approach by using an oncolytic VACV co-expressing IL2 with tumor-associated antigen epitopes for the activation and amplification of cytotoxic CD8+ T and CD4+ T cells in mice." (PMID 41050655, 2025). "In the ICI-treated PyMT tumor-bearing hCD4-KI mice, the 64Cu-CD4-Nb1 uptake was significantly higher (0.44 ± 0.04 %ID/ml) than in the ICI-treated PyMT tumor-bearing WT mice." (PMID 40561008, 2025). "GBM patients demonstrate elevated levels of CD4+ Tregs both systemically and within the tumor microenvironment, exemplified by CD4+CD25+FOXP3+CD45RO+ T cell phenotypes." (PMID 40243570, 2025). "Trials combining nanoparticle-delivered OX40 agonists (CD4+ T-cell costimulators) with anti-CTLA-4 antibodies show improved tumor regression in advanced cancers." (PMID 40860882, 2025). "The marked increase in IFN-γ in LCG CAR-T cells suggests enhanced tumor inhibitory activity, as CD4+ CAR-T cells can induce tumor cell death at distant sites in an IFN-γ-dependent manner." (PMID 39981247, 2025). "In preclinical studies, combinations of therapies such as anti-IL-1β and cabozantinib have been shown to enhance CD4 + effector T cell responses and increase naive T cells in tumor-draining lymph nodes." (PMID 41035074, 2025). "In parallel, the presence of Th1-skewed CD4+ T cells further enhances this immune response by promoting the effector mechanisms of the anti-tumor immune reaction." (PMID 40475020, 2025). "A negative correlation was observed between the proportion of infiltrating CD4+ T cells and arginase-1 expression in tumor-infiltrating neutrophils." (PMID 40358184, 2025). "The spleen and tumor tissues in chickens with MD showed a higher proportion of CD4+ T-cells than those of the uninfected controls." (PMID 40430752, 2025). "To solidify the mechanism of action of maraviroc in the LLC-bearing mice, we evaluated the tumor bed for infiltration of CD4+Foxp3+ T cells." (PMID 40553564, 2025). "When CD4+T/CD8+T is grouped based on tumor type and ICIs type, the heterogeneity among different subgroups decreases." (PMID 41244814, 2025). "XPro1595 reversed the tumor-induced decrease in axons and SCs, and suppressed Tregs, and CD4+ and CD8+ T cells." (PMID 41294802, 2025). "Both MRMI and T cell staining showed that anti-VISTA mAb treatment enhanced CD4+ T cell infiltration within the tumor core regions in SD hosts." (PMID 41041061, 2025).
tumor (continued). "Consistent with this, spatial transcriptomic analysis using Xenium showed differential localization of T cells (Cd3d, Cd3e, Cd3g, Cd8a, Cd8b1, and Cd4) within tumor sections of RPR2 and CRPR2 mice." (PMID 41353272, 2025). "For example, a study revealed that the depletion of myCAFs increased CD4+Foxp3+ Tregs infiltration into tumor, leading to an aggressive tumor progression." (PMID 40248695, 2025). "These vaccines also aid in the formation of immunological memory, thereby ensuring long-term protection against tumor recurrence through the promotion of CD4+ T-helper memory subsets." (PMID 40860882, 2025). "As CD4+ and CD8+ T cells are associated with the release of certain cytokines, they can be used as a marker of function within the tumor infiltrate." (PMID 41383591, 2025). "Meanwhile, an increase in CD4 T memory cells and a decrease in B cells were observed in the tumor immune microenvironment of STAS." (PMID 40786043, 2025). "Depletion studies confirmed that CD8 + and CD4 + T cells were essential for the anti-tumor effects, while NK cells played a lesser role." (PMID 41408568, 2025). "The results revealed a moderate increase in tumor‐infiltrating T lymphocytes, including both CD4+ and CD8+ T cells, in tumors from LZQ‐02‐023‐01‐treated mice compared to controls." (PMID 41114928, 2025). "In contrast, the low-risk group exhibited higher levels of immune cells generally associated with anti-tumor immunity, including B cells, CD8+ T cells, CD4+ T cells, M1 macrophages, neutrophils, and natural killer (NK) cells." (PMID 40697926, 2025). "Consistently, SPOP inhibition synergized with anti–PD-1 therapy to suppress tumor growth via enhanced CD4+IFN-γ+ T cell infiltration and further boosted CAR.CD19-T efficacy in B16-OVA tumors." (PMID 41148213, 2025). "Subsequently, we delineated distinct T cell subtypes in the tumour by flow cytometry, including naïve, effector and memory CD4 + /CD8 + T cells following the initial and second anti-PD-1 combination therapies." (PMID 39939955, 2025). "In breast cancer, pDC-expressed ICOS ligand facilitates CD4+ T-cell-mediated immunosuppression and tumor growth." (PMID 41394845, 2025). "CD8+ and CD4+ lymphocytes interact with both tumor cells and macrophages and determine the phenotype and the pro- or anti-tumor activity of the latter." (PMID 40112045, 2025). "Particularly, in the TME, it has been reported that the source of IL-2 switches from CD8+ T cells to CD4+ T cells during tumor progression." (PMID 40759573, 2025). "In humanized mouse models of orthotopic PC, treatment with these Engineered DCs led to significant tumor reduction, increased tumor-infiltrating lymphocytes (CD4+ and CD8+ T cells), and improved survival." (PMID 41295503, 2025). "In some cases, CD4+ T cell subtypes and M0 macrophages can promote tumor growth, which needs further study." (PMID 40088083, 2025). "The proportion of CD25+Foxp3+ Treg cells among activated CD4+ T cells was markedly reduced when co-cultured with TBX21-silenced tumor cells compared with sh-NC controls." (PMID 41573646, 2025). "Congruent with our current results, the therapeutic effect of anti-PD-1 and anti-CTLA4 was conditional on a CD4-driven anti-tumor response, while depletion of CD4+ cells still had a less pronounced effect on overall survival than depletion of CD8+ cells." (PMID 40102596, 2025). "Several early clinical trials utilizing unmodified naked tumor-antigen mRNA vaccines demonstrated their feasibility and safety, inducing antigen-specific CD4+ and CD8 + T-cell responses." (PMID 40629076, 2025). "These patients exhibit an “immune-excluded” phenotype, characterized by enhanced infiltration of Tregs and M0 macrophages, which can promote tumor growth, alongside significantly reduced infiltration of CD4+ T cells and natural killer (NK) cells." (PMID 41614774, 2025).
tumor (continued). "Lastly, an association between cSCC sLI CD4 and T status (p = 0.011), CD11c and N status (p = 0.041), CD68 and infiltrations depth (p = 0.018), as well as CD8 and CD11c and previous tumor (p = 0.006; p = 0.029, respectively) was observed." (PMID 41068337, 2025). "Cytotoxic CD4+ phenotypes (i.e., GZMB+, GZMK+, Prolif which is largely cytotoxic, and MAIT) comprised the vast majority of CD4+ cells in blood that matched a TCR with tumor." (PMID 40299576, 2025). "MHC class-II presentation activates CD4+ helper T cells that in turn help B cells to produce antibodies against tumor cells." (PMID 40427029, 2025). "Lymphocyte activation gene-3 (LAG3), an important inhibitory immune checkpoint in tumor immunity, is expressed on activated CD4 + and CD8 + effector and exhausted T cells, natural killer (NK) cells, and B cells induced by T cells." (PMID 40411616, 2025). "Using peptide screening methodology, nine HER3 peptides with capability to binding MHC-II were identified, and the HER3 peptide-pulsed DC vaccine generated specific CD4+ Th1 antitumor immune response impeding tumor growth in HER3-experssing mouse tumor models." (PMID 40342927, 2025). "Early deletion of c-Rel in conventional CD4 T cells can increase tumor burden and reduce responses to checkpoint blockade." (PMID 40370445, 2025). "CD4+ T cells enhance immune responses and anti-tumor effects by secreting cytokines and interacting with other immune cells." (PMID 40458394, 2025). "B cells, for example, can restrict tumor development by producing tumor-reactive antibodies, enhancing tumor elimination by NK cells and macrophage phagocytosis, and priming CD4+ and CD8+ T lymphocytes." (PMID 40805163, 2025). "CD4+ memory T cells play a crucial role in preserving immune memory, which is essential for establishing effective tumor defense and preventing tumor recurrence." (PMID 40438115, 2025). "The data from our systematic review on the CD4+ T cell infiltration in premalignant CR tumor tissues are controversial." (PMID 40149674, 2025). "Exosomes are also able to inhibit the function of immune cells involved in the anti-tumour response (dendritic cells, natural killer, CD4+ and CD8+ T lymphocytes) and to activate regulatory cell populations with immunosuppressive activities (Tregs and Bregs)." (PMID 41342689, 2025). "In contrast, the >600 mg tumor group displayed a limited NK cell treatment effect as expected, but did exhibit an improvement in OS upon depleting CD4+ cells alone." (PMID 39835538, 2025). "Tumor-derived exosomes carrying miRNAs can modulate dendritic cell maturation and thereby influence CD4+ T cell differentiation." (PMID 40647470, 2025). "The analysis of immune infiltration revealed a negative correlation between these core targets and most immune cell types in tumor tissues, such as B cells, CD4+ T cells, and macrophages." (PMID 40925573, 2025). "TNF-α and IFN-γ present in supernatants of TSLP-activated CD4+ T cells were required for PyMt tumor suppression." (PMID 40873585, 2025). "As the MHC-I and MHC-II are vital components of the antigen presentation machinery accountable for presenting neoantigen to CD8+ and CD4 + T lymphocytes, respectively, the downregulation leads to immune evasion deployed by tumour cells." (PMID 40911615, 2025). "The activated APCs migrate to lymph nodes, where they interact with CD8+ and CD4+ T cells, inducing cytotoxic T lymphocytes (CTLs) to secrete perforin and other effector molecules that directly kill tumor cells." (PMID 40872921, 2025). "Secondary tumor analysis revealed higher CD8+/CD4+ T cell infiltration and significant CD44+CD62L− effector memory T cell expansion, demonstrating systemic immune activation capable of suppressing distant tumors and establishing durable immune memory." (PMID 40892295, 2025).